MYO15A (myosin XVA)
Diseases named in the same sentence as MYO15A in open-access papers (continued):
Sharing a sentence is not in itself a finding about the gene and the disease.
Parkinson disease (1 paper, 2019). A progressive degenerative disorder of the central nervous system characterized by loss of dopamine producing neurons in the substantia nigra and the presence of Lewy bodies in the substantia nigra and locus coeruleus. "The results also showed a number of genes that decreased in an Mn dose-dependent manner which include genes involved in iron transport (TF), protective activity of telomeres (TERF2), neurosensory function (MYO15a, OR1F1), and neurological disease such as ADHD (DIRAS2) and Parkinson’s disease (FRK)." (PMID 31396262, 2019).
skin cancer (1 paper, 2018). "Even going beyond, SOSTDC1 and MYO15A have not been previously reported as skin cancer biomarkers." (PMID 29750795, 2018). "The vast heterogeneity of the sample collection with respect to diverse factors like platforms, origin, parts of the body, etc. positively influenced in the finding of 6 genes that had not previously related to skin cancer: SCGB2A1, CRYBA2, ANXA3, PCP4, SOSTDC1 and MYO15A." (PMID 29750795, 2018).
Waardenburg syndrome (1 paper, 2021). A disorder characterized by varying degrees of deafness and minor defects in structures arising from neural crest, including pigmentation anomalies of eyes, hair, and skin. "The woman had non-syndromic profound SNHI caused by bi-allelic MYO15A variants and the man had Waardenburg syndrome caused by a dominant MITF variant." (PMID 34943631, 2021).
cancer (2 papers, 2018). A tumor composed of atypical neoplastic, often pleomorphic cells that invade other tissues. "For example, several genes from the final part of the ranking, present specific clear information on MCC against the rest skin states as LGR5, POU4F1, SOSTDC1, KRT20, TGM3 and MYO15A genes, as their gene expression levels are opposite against to the other cancer-related skin states." (PMID 29750795, 2018). "For example, although MCC shows expression values contrary to the rest of skin states in the identified DEGs, there are genes like LGR5, POU4F1, SOSTDC1, KRT20 and MYO15A which are clearly postulated as differentiating genes in MCC diagnosing in comparison to other cancer-related skin states." (PMID 29750795, 2018).
neurological disease (2 papers, 2019 to 2022). "MYO15A helps define cellular morphology and has been associated with neurological disorders." (PMID 35573726, 2022).
MYO15A also shares sentences with these, for which no sentence is quoted: Hearing impairment (9 papers); autosomal recessive hearing loss (2); infection (2); Smith-Magenis syndrome (2); Ataxia (1); Blindness (1); Cerebellar atrophy (1); epilepsy (1); glioblastoma (1); Intellectual disability (1); movement disorder (1); myopathy (1); Palmoplantar keratoderma (1); peripheral neuropathy (1); retinopathy (1); sensorineural hearing loss (1); tumor (1).